VGF (VGF nerve growth factor inducible)
Diseases named in the same sentence as VGF in open-access papers (continued):
Sharing a sentence is not in itself a finding about the gene and the disease.
insulinoma (3 papers, 2015 to 2022). "Based on these findings, we stably transfected the INS-1-derived 832/13 rat insulinoma cell line with a plasmid containing the VGF promoter driving expression of luciferase, and used the resultant cell line to screen a 630,000 compound small molecule library." (PMID 32176701, 2020). "We developed an NKX6.1 pathway screen by stably transfecting 832/13 rat insulinoma cells with a VGF promoter-luciferase reporter construct, using the resultant cell line to screen a 630,000 compound chemical library." (PMID 32176701, 2020).
lung adenocarcinoma (3 papers, 2023 to 2025). A carcinoma that arises from the lung and is characterized by the presence of malignant glandular epithelial cells. "VGF, highly expressed in a subgroup of lung adenocarcinomas, has been linked to EGFR-TKI resistance and epithelial-to-mesenchymal transition." (PMID 40592939, 2025). "By way of contrast, with the treatment of HDAC1 inhibitor, VGF expression is induced in lung adenocarcinoma cells." (PMID 38528565, 2024).
memory impairment (3 papers, 2022 to 2024). "VGF is also a target of interest which was recently found to partially rescue memory impairment and neuropathology in 5xFAD mice." (PMID 37188718, 2023). "Mice overexpressing VGF showed behavioral abnormalities, such as hyperactivity, memory impairment, lower sociality, and higher depressive state, as well as morphological alterations, like smaller brain weight, expansion of the lateral ventricle, striatal morphological abnormalities." (PMID 38493246, 2024).
mood disorder (3 papers, 2011 to 2021). A cognitive disorder a disturbance in which the person's mood is hypothesized to be the main underlying feature. "Recently, Cattaneo observed that depressed patients without treatment showed lower levels of VGF mRNA when compared with controls, which indicates a role for VGF in the pathophysiology of mood disorders." (PMID 22654714, 2011).
non-small cell lung carcinoma (3 papers, 2017 to 2024). A group of at least three distinct histological types of lung cancer, including non-small cell squamous cell carcinoma, adenocarcinoma, and large cell carcinoma. "Here, we demonstrate that VGF is epigenetically modified in non-small cell lung cancer tissues compared to corresponding tumor-free lung tissues from the same donors by using methylome bead chip analyses." (PMID 29209432, 2017). "After that, lines of evidence have demonstrated VGF as one of the differentially expressed genes for annotating immune cell infiltration profile and prognostic values in malignancies such as non-small cell lung carcinoma (NSCLC), colorectal carcinoma (CRC) and thyroid carcinoma." (PMID 38528565, 2024).
type 2 diabetes (3 papers, 2015 to 2020). "The studies suggest that loss of VGF could be involved in the development of islet beta cell dysfunction in type 2 diabetes." (PMID 31058853, 2019).
bipolar disorder (2 papers, 2017 to 2019). A disorder of the brain that causes unusual shifts in mood, energy, activity levels and the ability to carry out day-to-day tasks. "Among these were BDNF, VGF, WFS1, DUSP6, CRHBP, MAOA, and RELN, which have previously been implicated in bipolar disorder." (PMID 31114610, 2019).
Brain atrophy (2 papers, 2017 to 2023). Partial or complete wasting (loss) of brain tissue that was once present. "A fifth and final category of changes included the onset of brain atrophy and decreases in neuronal and neurosecretory proteins such as secretogranin-2, VGF, thy1 membrane glycoprotein, and neuropentraxin and its receptor, suggesting frank synaptic and neuronal loss." (PMID 37550416, 2023).
COVID-19 (2 papers, 2022 to 2023). A disease caused by infection with severe acute respiratory syndrome coronavirus 2. "Furthermore, VGF is associated with synaptic transmission, and a study in two different brain regions from COVID-19 patients showed enriched synaptic neurotransmitter release." (PMID 38002279, 2023). "One of these studies showed decreased VGF (VGF nerve growth factor) expression in CSF from COVID-19 patients." (PMID 38002279, 2023).
Encephalopathy (2 papers, 2011 to 2015). Encephalopathy is a term that means brain disease, damage, or malfunction. "Because VGF is essential for feeding behavior and energy expenditure, an enormous number of possible mechanisms whereby a deficiency of VGF might contribute to encephalopathy susceptibility or modify the phenotype of the clinical syndrome of encephalopathy are possible." (PMID 21838886, 2011). "We found a 4.8-kDa peptide fragment from a neurosecretory protein VGF precursor (VGF4.8) in CSF was identified as a novel biomarker for encephalopathy using Surface-enhanced laser desorption/ionization time-of-flight mass spectrometry (SELDI-TOF MS)." (PMID 21838886, 2011). "After purification and identification of the 4.8-kDa protein, a 4.8-kDa proteolytic peptide fragment from the neurosecretory protein VGF precursor (VGF4.8) was identified as a novel biomarker for encephalopathy." (PMID 21838886, 2011). "A 4.8-kDa proteolytic peptide fragment from the protein of a neurosecretory protein VGF was identified as a novel biomarker for encephalopathy (VGF4.8)." (PMID 21838886, 2011). "In the present study, SELDI-TOF MS was employed to identify a possible biomarker in cerebrospinal fluid for acute encephalopathy and a proteolytic peptide fragment from the neurosecretory protein VGF precursor was identified as a novel biomarker for encephalopathy." (PMID 21838886, 2011).
glioma (2 papers, 2019 to 2022). A benign or malignant brain and spinal cord tumor that arises from glial cells (astrocytes, oligodendrocytes, ependymal cells). "A recent study identified VGF as a key player in the bidirectional influence between Glioma stem cells (GSC) and their differentiated progeny (DGCs, differentiated glioma cells)." (PMID 35884475, 2022). "This was motivated by a recent study that showed that VGF is an important regulator of glioma stem cells." (PMID 31682594, 2019).
Huntington disease (2 papers, 2020 to 2022). Huntington disease (HD) is a rare neurodegenerative disorder of the central nervous system characterized by unwanted choreatic movements, behavioral and psychiatric disturbances and dementia. "VGF and its derived peptide have neuroprotective effects in several pathological models such as Huntington's disease." (PMID 32174778, 2020).
Insulin resistance (2 papers, 2014 to 2023). Increased resistance towards insulin, that is, diminished effectiveness of insulin in reducing blood glucose levels. "Taken together, our data support Blagosklonny's hyperfunction hypothesis of aging, implicating that T cells are involved in the pathogenesis of insulin resistance and add VGF as a novel biomarker which becomes upregulated by rising HbA1c and the BMI." (PMID 25013207, 2014).
memory (2 papers, 2017 to 2024). The activities involved in the mental information processing system that receives (registers), modifies, stores, and retrieves informational stimuli. "VGF knockout mice display behavioral abnormalities such as higher depressive behavior and memory dysfunction." (PMID 28680036, 2017). "In addition, previous studies found that hippocampal VGF overexpression rescued reduced PSD95 levels in 5xFAD that correlated with a reduction in their memory deficits." (PMID 39006222, 2024).
neuropathic pain (2 papers, 2008 to 2013). Chronic pain caused by damage to nerve fibers. "Neuropeptide precursor VGF is commonly up-regulated in sensory neurons in a number of neuropathic pain models." (PMID 24106277, 2013). "This peptide has been shown to be associated with synaptic strengthening and learning in the hippocampus and while it is known that VGFmRNA is upregulated in dorsal root ganglia following peripheral nerve injury, the role of this VGF peptide in neuropathic pain has yet to be investigated." (PMID 19077191, 2008). "Since VGF is highly regulated in the DRG and dorsal horn following peripheral nerve injury, we hypothesized that it may have a role in the behavioral hypersensitivity to touch and cold that is a characteristic of neuropathic pain." (PMID 19077191, 2008).
neuropathy (2 papers, 2023). A disorder affecting the nervous system that manifests with pain, tingling, numbness, and/or muscle weakness. "VGF is known to be upregulated in HIV-associated neuropathy and can lead to weakness." (PMID 38002279, 2023). "VGF is a peptide that is increased with nerve growth factor and highly expressed in the peripheral and central nervous system following neuropathy." (PMID 37298117, 2023).
ovarian carcinoma (2 papers, 2013 to 2020). A malignant neoplasm originating from the surface ovarian epithelium. "Overexpression of VGF inhibits colony formation of ovarian cancer cells, however, VGF promoter hypermethylation correlates with better patient survival." (PMID 32260415, 2020).
prostate carcinoma (2 papers, 2019 to 2025). A carcinoma that arises from epithelial cells of the prostate gland. "The expression of genes in the gene-based risk score was further validated using clinical samples, and VGF was found to play a significant role in prostate cancer progression." (PMID 40592939, 2025). "We identified a novel gene risk panel comprising six genes (SSTR1, CA14, HJURP, KRTAP5-1, VGF, and COMP) for prostate cancer risk classification." (PMID 40592939, 2025). "This was motivated by our observation that VGF showed increased expression in prostate cancer patients with early relapse and further triggered by recent studies that highlighted the importance of VGF in different types of cancer." (PMID 31682594, 2019). "Additional preclinical and clinical studies are required to further validate the role of VGF and other candidate genes as potential biomarkers for the prediction of radiotherapy responses and as potential targets for radiosensitization of prostate cancer." (PMID 31682594, 2019). "Despite these advances, the specific contribution of VGF to prostate cancer (PCa) progression remains unclear." (PMID 40592939, 2025). "We found that VGF was significantly upregulated in DU145 and LNCaP prostate cancer radioresistant cell lines in our genome-wide gene expression analysis (average expression difference of 2.85 in DU145 and 1.37 in LNCaP, t-tests: P < 0.01, S7 Table)." (PMID 31682594, 2019). "Finally, we also considered the prostate cancer cell line PC3 and could confirm the efficiency of VGF knockdowns and we also observed a moderately increased radiosensitivity in response to VGF knockdowns (e.g. t-test: siRNA VGF #2 vs. negative control: P < 0.03 at 4 Gy)." (PMID 31682594, 2019).
autism (1 paper, 2022). Persistent deficits in social interaction and communication and interaction as well as a markedly restricted repertoire of activity and interest as well as repetitive patterns of behavior. "No gene was formally significant after correction for multiple testing, but three genes possibly related to autism were significant at P < 0.001, FOXP1, ARHGAP33 and CDH9, along with VGF which may also be of psychiatric interest." (PMID 33893496, 2022).
bladder (1 paper, 2014).
bladder cancer (1 paper, 2014). "VGF mRNA expression was significantly decrease in bladder cancers and VGF over expression in bladder cancer cells inhibit cell growth." (PMID 24830820, 2014). "Overexpression of VGF in comparison with empty vector was confirmed by real-time RT-PCR in J82 and SCaBER bladder cancer cell lines." (PMID 24830820, 2014). "To define the biologic consequences of VGF on cell proliferation and colony formation, we ectopically introduced VGF into two bladder cancer cell lines (J82 and SCaBER) and performed MTT and colony formation assays." (PMID 24830820, 2014). "In our study, promoter methylation of VGF inversely correlated with loss of gene expression in bladder cancer cell lines and primary UCC, and re-activation of VGF could be obtained by inhibiting DNA methylation with 5-Aza-dC." (PMID 24830820, 2014). "Strong anti-proliferative activity of VGF was also observed in bladder cancer cell lines." (PMID 24830820, 2014). "Forced expression of VGF in bladder cancer cell lines inhibited cell growth." (PMID 24830820, 2014). "In an extended study using primary UCC tissues with paired normal, we successfully identified VGF as a UCC specific hypermethylated gene (P=0.009) and provided biologic evidence of growth inhibitory effect of VGF in bladder cancer cell lines." (PMID 24830820, 2014). "VGF expression vector (pCMV6-AC–VGF–GFP, OriGene Technologies, Inc., Rockville, MD), as well as the empty vector (pCMV6-AC-GFP, OriGene Technologies, Inc.)were transfected into J82 and SCaBER bladder cancer cell lines that have fully methylated VGF promoter of our analyzed region and VGF silenced." (PMID 24830820, 2014).
cystadenoma (1 paper, 2013). A benign or borderline cystic epithelial neoplasm arising from the glandular epithelium. "Based on the availability of samples and novelty of genes for OC and methylation frequencies in the training set, we selected 2 genes (VGF and PGP9.5) to test in an independent cohort of samples consisting of 372 carcinomas, 18 borderline tumors and 17 cystadenomas." (PMID 24086249, 2013).
endothelial dysfunction (1 paper, 2016). In vascular diseases, endothelial dysfunction is a systemic pathological state of the endothelium (the inner lining of blood vessels) and can be broadly defined as an imbalance between vasodilating and vasoconstricting substances produced by (or acting on) the endothelium. "In severe pulmonary disease, VGF levels decline as a result of the endothelial dysfunction and exhaustion of the repair mechanisms." (PMID 27928450, 2016).
Fanconi anemia (1 paper, 2025). Fanconi anemia (FA) is a hereditary DNA repair disorder characterized by progressive pancytopenia with bone marrow failure, variable congenital malformations and predisposition to develop hematological or solid tumors. "PCSK1N was enriched in the cytosolic DNA‐sensing pathway, Th17 cell differentiation, and phagosome pathway, while VGF was associated with the Fanconi anemia pathway, DNA replication, and cell cycle pathway." (PMID 40600620, 2025).
Impaired glucose tolerance (1 paper, 2024). An abnormal resistance to glucose, i.e., a reduction in the ability to maintain glucose levels in the blood stream within normal limits following oral or intravenous administration of glucose. "Hypothalamic VGF expression has been shown to be regulated by both feed restriction and leptin, with VGF knockout mice displaying increased adiposity, reduced energy expenditure and impaired glucose tolerance." (PMID 39095703, 2024).
Infertility (1 paper, 2015). "The role of VGF signaling in reproduction was inferred from the observation that VGF gene deletion resulted in infertility in both male and female mice." (PMID 25699015, 2015).
interstitial cystitis (1 paper, 2014). A rare chronic debilitating urogenital disease characterized by urinary frequency, urgency, and pelvic pain. "Deregulation of VGF associated gene was reported in bladder tissue of interstitial cystitis; however, direct correlation of VGF with UCC is still not reported." (PMID 24830820, 2014).
liver fibrosis (1 paper, 2024). "This indicated that tumor‐secreted VGF may interact with TGFBR2 of HSCs and then activate the canonical TGF‐β‐SMAD signaling pathway to trigger liver fibrosis." (PMID 39422674, 2024).
migraine (1 paper, 2019). "Intriguingly, six precursor proteins (determined by the overlap between protein classes among treatment groups from PANTHER analysis) were common to both migraine and OIH treatments in both cohorts, and include SCG, PENK, proCGRP, VGF, and Peptidyl-prolyl-cis-trans-isomerase-A." (PMID 31649062, 2019).
nicotine dependence (1 paper, 2025). Physical and psychological dependence on nicotine. "Previous reports indicated that SLC2A13, BHLHE41, VGF and AHR variants are associated with heavy and problem drinking in patients as well as with nicotine dependence in tobacco users." (PMID 39880903, 2025).
oral carcinoma (1 paper, 2024). "The combined expression of VGF and IL23R emerges as a potent predictor of survival in oral carcinoma cases, suggesting potential implications for future therapeutic strategies." (PMID 38528565, 2024).
osteoarthritis (1 paper, 2021). A noninflammatory degenerative joint disease occurring chiefly in older persons, characterized by degeneration of the articular cartilage, hypertrophy of bone at the margins and changes in the synovial membrane. "Our finding is aligned with reports that targeting VGF system of signaling and receptor molecules can ameliorate osteoarthritis pain, and is associated with neuropathic pain." (PMID 34680965, 2021).
ovarian tumor (1 paper, 2013). "In our study, PH of VGF correlated with loss of gene expression in cancer cell lines and primary ovarian tumor, and re-expression of VGF could be obtained by inhibiting DNA methylation with 5-aza-dC." (PMID 24086249, 2013).
pancreatic neuroendocrine neoplasm (1 paper, 2021). A neoplasm with neuroendocrine differentiation that arises from the pancreas. "H19 regulated the VGF expression level, which promoted pancreatic neuroendocrine neoplasm cell proliferation, migration and invasion." (PMID 34977037, 2021). "In summary, these results demonstrated that H19 could promote pancreatic neuroendocrine neoplasm progression via the VGF-mediated PI3K/Akt/CREB pathway." (PMID 34977037, 2021).
pancreatic neuroendocrine tumor (1 paper, 2023). Pancreatic endocrine tumor, also known as pancreatic neuroendocrine tumor (PNET), describes a group of endocrine tumors originating in the pancreas that are usually indolent and benign, but may have the potential to be malignant. "Previous studies have shown that VGF promotes the malignant phenotype of pancreatic neuroendocrine tumors." (PMID 37742030, 2023).
tauopathies (1 paper, 2025). "In our ProPPr data, VGF had a significantly higher association with phospho-tau lesions in PiD compared to PSP with a trend for increase compared to other tauopathies." (PMID 40082954, 2025). "To further examine this finding, we performed co-immunofluorescence of VGF with phospho-tau in the four major tauopathies, as well as normal controls." (PMID 40082954, 2025).
testicular cancer (1 paper, 2014). A primary or metastatic malignant neoplasm that affects the testis. "Recently, we identified VGF as a cancer specific methylated gene in our “Cancer Methylome” discovery approach and also reported VGF as an ovarian and testicular cancer specific methylated gene by candidate gene approach, a strategy which was used in the present study." (PMID 24830820, 2014).
uveal melanoma (1 paper, 2024). A melanoma derived from melanocytes of the uveal tract. "The secreted neuropeptide precursor, VGF, has been identified as a facilitator of the progression and metastasis of Gαq mutant Uveal melanoma (UM) through intricate autocrine and paracrine signaling loops." (PMID 39422674, 2024).